GPR39 (G protein-coupled receptor 39)
Diseases named in the same sentence as GPR39 in open-access papers (continued):
Sharing a sentence is not in itself a finding about the gene and the disease.
prostate carcinoma (7 papers, 2010 to 2022). A carcinoma that arises from epithelial cells of the prostate gland. "In prostate cancer cells, ZnR/GPR39 was also associated with upregulation of ERK1/2 and PI3K phosphorylation, and enhanced cell growth." (PMID 34572390, 2021). "The zinc-sensing receptor GPR39 has been shown to exist widely in neurons, colon cells, keratinocytes, pancreatic cells, prostate cancer cells, salivary gland cells, and bone cells." (PMID 36292986, 2022). "The activation of ZnR/GPR39 in keratinocytes, colon cells, and prostate cancer cells can increase the phosphorylation levels of ERK and AKT, thereby promoting cell growth." (PMID 36292986, 2022). "For example, in androgen-insensitive prostate cancer cell lines, Zn2+-activating GPR39 can increase the expression and phosphorylation of AKT and activate the PI3K signal pathway." (PMID 36292986, 2022). "ZnR/GPR39 activation in prostate cancer cells was shown to promote cell growth through PI3K dependent upregulation of ERK and AKT phosphorylation." (PMID 32850402, 2020). "Most prominently, ZnR/GPR39 activity was described in prostate cancer, skin keratinocytes, and colon epithelial cells, where zinc is essential for cell growth, wound closure, and barrier formation." (PMID 29389900, 2018). "ZnR/GPR39 activation in keratinocytes, colonocytes, and prostate cancer cells was shown to upregulate ERK and AKT phosphorylation and thereby cell growth." (PMID 29389900, 2018). "For example, following ZnR/GPR39 desensitization the Zn2+-dependent ERK1/2 phosphorylation was diminished in prostate cancer cells." (PMID 29389900, 2018). "Extracellular Zn2+ via activation of ZnR/GPR39 in the prostate cancer cell line PC-3 enhances expression of S100A4, a protein that is thought to enhance metastatic prostate cell proliferation and angiogenesis." (PMID 29389900, 2018). "In prostate cancer, however, when the Zn2+ concentration is decreased, ZnR/GPR39 may be re-sensitized, such that extracellular Zn2+ binding to it will activate Ca2+ signaling, leading to proliferation." (PMID 34572390, 2021). "Activity of ZnR/GPR39 in tissues relevant to Zn2+ signaling has been identified in neurons, colon epithelial cells (colonocytes), skin epidermal cells (keratinocytes), pancreatic cells, prostate cancer cells, salivary gland cells, and in bones." (PMID 29389900, 2018). "Consistent with this, when ZnR/GPR39 is desensitized, the phosphorylation of Zn2+-dependent ERK1/2 in prostate cancer cells was shown to decrease." (PMID 36292986, 2022). "A previous study has shown that ZnR/GPR39 mediates the Zn2+-dependent activation of mitogen-activated protein kinase (MAPK) and PI3K, to induce S100A4 expression and prostate cancer cell invasiveness." (PMID 29069865, 2017). "However, following ZnR/GPR39 desensitization, ERK phosphorylation was diminished in prostate cancer cells." (PMID 32850402, 2020). "Activation of ZnR/GPR39 signaling was monitored in androgen-independent, but not androgen-dependent, prostate cancer cells." (PMID 29389900, 2018).
Obesity (6 papers, 2007 to 2020). Accumulation of substantial excess body fat. "GPR39 deficiency has been reportedly associated with obesity and reduced lipolysis in adipocytes." (PMID 32085416, 2020). "GPR39 is receptor for obestatin (belonging to the ghrelin receptor family), involved in regulation of appetite and glucose homeostasis and associated with obesity." (PMID 28396702, 2017). "This establishes Gpr39 as a candidate for this pleiotropic QTL affecting both obesity and plasma lipid levels, even in light of the fact of recent observations clouding its role." (PMID 17653278, 2007). "However, GPR39 may not only protect islets from apoptosis but may also be involved in proliferative, adaptive responses of the islets as Tremblay and coworkers found that Gpr39-deficient mice do not display the normal pancreatic islet hyperplasia in response to diet-induced obesity." (PMID 22164158, 2011).
Alzheimer disease (5 papers, 2018 to 2024). A progressive, neurodegenerative disease characterized by loss of function and death of nerve cells in several areas of the brain leading to loss of cognitive function such as memory and language. "Dysregulation of oxylipins metabolism has been implicated in both Alzheimer’s disease and type 2 diabetes, suggesting that oxylipin mechanism in GPR39 KO mice might be shared with VCI pathophysiology." (PMID 35875352, 2022). "The high level of hippocampal GPR39 expression, and GPR39’s participation in hippocampal zinc neurotransmission, make both a candidate in Alzheimer’s disease (AD) pathogenesis and potential therapeutic targets." (PMID 34360964, 2021). "Numerous lines of evidence indirectly implicate GPR39 in Alzheimer’s disease (AD)." (PMID 34360964, 2021). "Indeed, the AD11 mouse model of Alzheimer’s disease demonstrated that neurons high in Aβ plaques had downregulated KCC2 mRNA, potentially from decreased GPR39 activation, and exhibited such predicted depolarizing GABAA currents in CA1 pyramidal neurons." (PMID 34360964, 2021). "This decrease in ZnR/GPR39-dependent signaling, reducing the homeostatic activation of KCC2, may serve as a link to the increased incidence of seizure found in Alzheimer’s disease patients compared to the general population." (PMID 29389900, 2018).
Anxiety (5 papers, 2020 to 2025). Intense feelings of nervousness, tension, or panic often arise in response to interpersonal stresses. "GPR39 is highly expressed in the hippocampus and amygdala, regions that encode fear, anxiety-provoked behavior, and stress memory." (PMID 34360964, 2021). "GPR39 was also shown to modulate anxiety-like behavior, and GPR39 expression was increased by antidepressant administration." (PMID 32455839, 2020). "GPR39 KO mice demonstrate increased anxiety behavior relative to control littermates." (PMID 34360964, 2021).
Cognitive impairment (5 papers, 2019 to 2023). Abnormal cognition is characterized by deficits in thinking, reasoning, or remembering. "In vivo, rats fed a zinc-deficient diet for 4 weeks showed increased cognitive deficits and decreased GPR39 brain expression after induction of developmental seizures compared to rats fed normal zinc diets." (PMID 34360964, 2021). "Our present findings indicate that a zinc-deficient diet can further lead to decreased expression of GPR39 in the hippocampus, which in turn aggravates cognitive impairment." (PMID 31551684, 2019). "Although no direct evidence has shown that the GPR39 SNP is associated with cognitive impairment, pure SNPs in the GPR39‐encoding gene may accelerate the progression of white matter hyperintensities." (PMID 36942516, 2023). "The primary goal of our study was to determine if GPR39 plays a role in cognitive impairment related to HFD." (PMID 35875352, 2022). "On the other hand, Resolvin D1 is anti-inflammatory and its induction by GPR39 is likely a compensatory response to protect against neuroinflammation and cognitive impairment." (PMID 35875352, 2022). "Taken together, these results indicate that GPR39 deletion impairs spatial memory retention and suggest a protective role for GPR39 against cognitive impairment." (PMID 35875352, 2022). "Postmortem human brain samples from cognitively intact individuals and patients with mild cognitive impairment (MCI) were recently evaluated using GPR39 immunohistochemistry." (PMID 34360964, 2021). "Finally, while mechanistic inquiries are beyond the scope of the current study, the data presented here is the first description of cognitive impairment in GPR39 KO mice." (PMID 35875352, 2022). "We tested the hypothesis that GPR39 plays a protective role against cognitive impairment by modulating CBF and neuroinflammation." (PMID 35875352, 2022). "We tested the hypothesis that GPR39 plays a protective role against high-fat diet (HFD)-induced cognitive impairment, in part mediated via oxylipins actions on cerebral blood flow (CBF) and neuroinflammation." (PMID 35875352, 2022). "Therefore, in this study, we used GPR39 mutant mice to determine if GPR39 deficiency affects cognition at baseline and alters HFD-induced cognitive impairment." (PMID 35875352, 2022). "Mechanistically, GPR39 deletion may lead to cognitive impairment through vascular or inflammatory mechanisms." (PMID 35875352, 2022). "In the current study, we used GPR39 mutant mice, with homozygous (KO) and heterozygous (Het) deletion of GPR39, to test the hypothesis that it plays a protective role against cognitive impairment in the HFD mouse model of metabolic syndrome." (PMID 35875352, 2022). "However, our data does not support a role for reduced CBF in cognitive impairment related to GPR39 deficiency." (PMID 35875352, 2022). "Based on the genetic association of GPR39 SNPs with markers of VCI and changes in GPR39 expression in postmortem human brain, we tested the hypothesis that GPR39 plays a protective role against cognitive impairment, mediated in part via oxylipins actions on CBF and neuroinflammation." (PMID 35875352, 2022). "We conclude that GPR39 plays a role in spatial memory retention and protects against HFD-induced cognitive impairment in part by modulating inflammation and AA-derived oxylipins." (PMID 35875352, 2022). "Furthermore, it was observed that the zinc diet-treated group increased the expression of GPR39 and BMP protein, and improved cognitive impairment, while it showed to decrease hippocampal mossy fiber regenerative sprouting." (PMID 34645465, 2021). "We recently reported that GPR39 is an oxylipins receptor; therefore, we report here valuable and unique oxylipins data that point to specific pathways altered in brain and plasma by HFD and GPR39 deletion, as potential mediators of cognitive impairment in these models." (PMID 35875352, 2022).
colitis (5 papers, 2018 to 2022). Inflammation of the colon. "Consistent with this, compared with wild-type mice, GPR39 knockout mice had low levels of ZO-1 and occludin expression in the colon and were highly susceptible to DSS-induced colitis." (PMID 36292986, 2022). "GPR39 sensing of extracellular zinc appears to affect the severity of colitis." (PMID 30984791, 2019). "A similar effect on colon epithelial cells was observed in a model of colitis, where the recovery of colon tissue in mice lacking ZnR/GPR39 was impaired." (PMID 34572390, 2021). "Mice lacking GPR39 showed increased mortality after the induction of experimental colitis." (PMID 30984791, 2019). "In addition, in a cholera toxin model of diarrhea or a dextran sodium sulfate model of colitis, ZnR/GPR39-dependent pathways were not activated following dietary Zn2+ depletion." (PMID 29389900, 2018). "In addition, during the recovery from colitis induced by dextran sodium sulfate (DSS), cell proliferation increased in GPR39-expressing mice, but no similar phenomenon was observed in GPR39-deficient mice." (PMID 36292986, 2022).
esophageal squamous cell carcinoma (5 papers, 2011 to 2021). Esophageal squamous cell carcinoma (ESCC) is a type of esophageal carcinoma (EC) that can affect any part of the esophagus, but is usually located in the upper or middle third. "Further evidence for the role of ZnR/GPR39 in cancer comes from a study of esophageal squamous cell carcinoma (ESCC) shows that overexpression of GPR39 is associated with lymph node metastasis." (PMID 34572390, 2021). "Meanwhile, over-expression of GPR39 contributes to development of esophageal squamous cell carcinoma; while TMEM16A also serves as a marker for gastrointestinal stromal tumors (GIST)." (PMID 23133519, 2012). "Indeed, the GPR39 receptor was found to be overexpressed in primary esophageal squamous cell carcinomas (ESCCs), which was significantly associated with lymph node metastasis and advanced TNM stage, suggesting that GPR39 plays an important tumorigenic role in the development and progression of ESCC." (PMID 26716511, 2016).
breast carcinoma (4 papers, 2018 to 2023). "To determine if activation of ZnR/GPR39 signaling controls breast cancer cell growth and invasion, we initially compared the Zn2+-dependent cell growth rates in ZnR/GPR39-expressing TAMR cells, and MCF-7 cells deficient in this receptor." (PMID 29802348, 2018). "We then asked whether ZnR/GPR39 expression is associated with human breast cancer malignancy." (PMID 29802348, 2018). "Changes in the expression of ZnR/GPR39 in breast cancer cells following loss of the ER signaling may provide a circumventing pathway for metabotropic signaling activation and enhanced cell growth in breast cancer." (PMID 29802348, 2018). "Experiments in the human breast cancer cell line MCF-7, for instance, revealed that ZnR/GPR39 is active in breast cancer cells, and activates MAPK/ERK and PI3K/AKT signaling pathways, resulting in increased proliferation and invasiveness." (PMID 36902254, 2023). "Recently, our lab has determined that ZnR/GPR39 is present in breast cancer cells, and upon activation by extracellular Zn2+, increases cell proliferation." (PMID 34572390, 2021). "Altogether the results presented support an important role for ZnR/GPR39 in mediating Zn2+-signaling that is leading to enhanced growth and invasiveness of breast cancer cells." (PMID 29802348, 2018). "We then asked if the enhanced activity of PI3K/AKT and MAPK/ERK1/2 pathways in breast cancer cells can be mediated via ZnR/GPR39." (PMID 29802348, 2018). "Consistently, analysis of two breast cancer patient cohorts, GDS4057 and TCGA, indicated that in ER-negative tumors higher ZnR/GPR39 mRNA levels are associated with more aggressive tumors." (PMID 29802348, 2018). "We then specifically addressed the role of ZnR/GPR39 in mediating the Zn2+-dependent Ca2+ response in breast cancer cells by either overexpression or siRNA silencing of GPR39 (siGPR39)." (PMID 29802348, 2018). "ZnR/GPR39 activity has been found to be enhanced in breast cancer." (PMID 36421686, 2022). "A recent study reports that ZnR/GPR39 activation in breast cancer cells leads to activation of K+/Cl- cotransporter KCC3, which may locally affect cell volume resulting in formation of protrusions." (PMID 34572390, 2021). "Furthermore, consistent with a role for ZnR/GPR39 in breast cancer progression, we demonstrated an increase in expression of the receptor in biopsies from higher grade mammary tumors." (PMID 34572390, 2021). "Studies in breast cancer cells show that KCC3 is upregulated by ZnR/GPR39 in the ER+ cell lines." (PMID 34572390, 2021). "In addition, using human breast cancer tissue staining, we also show an increase in ZnR/GPR39 expression in grade 3 tissues compared to grade 2." (PMID 29802348, 2018). "As such, ZnR/GPR39 may provide an upstream target for novel therapeutic approaches for hormone resistant breast cancer." (PMID 29802348, 2018). "Activation of ZnR/GPR39 by endogenous Zn2+ in breast cancer tissue may occur following specific release of Zn2+ from vesicles or cell injury and death." (PMID 29802348, 2018). "Nevertheless, and in agreement with reports describing changes in vesicular Zn2+ as well as “elemental zinc” in breast cancer cells, potential Zn2+ release from protein or vesicles may be sufficient for triggering ZnR/GPR39 activation." (PMID 29802348, 2018). "We, therefore, hypothesized that ZnR/GPR39 may be an upstream regulator of breast cancer cell proliferation." (PMID 29802348, 2018). "Expression of ZnR/GPR39 was increased in grade 3 human breast cancer biopsies compared to grade 2." (PMID 29802348, 2018). "Thus, we suggest that changes in Zn2+ homeostasis in breast cancer tissue, together with increased ZnR/GPR39 expression yield an alternative pathway leading to cell growth." (PMID 29802348, 2018). "Our study suggests that in breast cancer tissue, elevated Zn2+ levels and increased ZnR/GPR39 expression may provide an alternative pathway to PI3K and MAPK activation." (PMID 29802348, 2018).
breast carcinoma (continued). "Thus, ZnR/GPR39 may provide an alternative pathway that contributes to increased malignancy in breast cancer." (PMID 29802348, 2018). "We found that Zn2+-dependent cell growth in the TAMR, ZnR/GPR39-expressing, breast cancer cells was much faster compared to MCF-7 cells." (PMID 29802348, 2018). "We also compared proliferation rates of ZnR/GPR39 expressing MDA-MB-453 and BT20 breast cancer cells following daily treatment with Zn2+ (200 μM, 2 min) or EDTA (100 μM, 2 min)." (PMID 29802348, 2018). "The Zn2+-sensing G-protein coupled receptor, ZnR/GPR39, triggers signaling leading to cell growth, but a role for this receptor in breast cancer in unknown." (PMID 29802348, 2018). "Thus, Zn2+ and ZnR/GPR39, via a Gαq-dependent pathway, upregulate the PI3K/AKT and MAPK pathways in TAMR and BT20 breast cancer cells." (PMID 29802348, 2018). "Cell signaling and subsequent increases in proliferation rate were triggered by transient extracellular Zn2+ treatment in ERα-negative breast cancer cells expressing a functional ZnR/GPR39." (PMID 29802348, 2018). "Our results suggest a role for ZnR/GPR39 in mediating Ca2+ signaling in ER negative breast cancer cells, but not in cells that are ER positive." (PMID 29802348, 2018). "Thus, we suggest ZnR/GPR39 as a potential therapeutic target for combination treatment in breast cancer, particularly relevant in ER negative tumors." (PMID 29802348, 2018). "The data presented here support our hypothesis that ZnR/GPR39 mediates signaling pathways leading to aggressive growth in breast cancer cells, particularly in the absence of the estrogen receptor pathway." (PMID 29802348, 2018).